MUC6 (mucin 6, oligomeric mucus/gel-forming (gene/pseudogene))
Diseases named in the same sentence as MUC6 in open-access papers (continued):
Sharing a sentence is not in itself a finding about the gene and the disease.
pancreatic cancer (9 papers, 2004 to 2023). "Mechanistically, CASC2 sponged miR-24 and relieved the repressive effects of miR-24 on MUC6 to suppress pancreatic cancer growth and progression." (PMID 34178644, 2021). "Cancer susceptibility candidate 2 (CASC2) exerted tumor-suppressive effects through regulation of miR-24/MUC6 axis in pancreatic cancer cells." (PMID 34178644, 2021). "Driver genes have been identified as the building blocks in pancreatic cancer, and emerging data suggested that driver gene K-Ras involved in the process of splicing control, such as mucin 6 (MUC6), hepatocyte growth factor (HGF), VEGFR-2, and VEGFB." (PMID 31552163, 2019). "Furthermore, our recent in vitro analysis of pancreatic cancer lines showed that MUC6 expression significantly suppressed cancer cell proliferation, motility and invasiveness, and that αGlcNAc-glycosylated MUC6 had significantly more robust anti-cancer effects." (PMID 38062108, 2023). "The apomucins MUC1, MUC5B, MUC5AC, and MUC6 are expressed in the normal pancreas; MUC1, MUC2, and MUC4 are upregulated in pancreatic tumours, whereas MUC5B, MUC5AC, and MUC6 are slightly downregulated." (PMID 14760381, 2004). "Interestingly, upregulation of MUC6 expression was found in the early stage and absent in the late stage of pancreatic cancer." (PMID 32695780, 2020).
breast carcinoma (8 papers, 2012 to 2023). "Interestingly, we found significant enrichment of a variant in the MUC6 gene in Breast Cancer and in Colon cancer, both of which are of unknown effect." (PMID 36497297, 2022). "MUC5AC and MUC6 share similar functions in protecting the mucosal membrane; however, reports on their expressions in breast cancer are limited." (PMID 27846863, 2016). "Among the four polymerizing mucins MUC2, MUC5B, MUC5AC, and MUC6 whose altered expression has been reported in breast cancer tissues, the role of MUC5B is poorly documented." (PMID 23056409, 2012). "The proportion of cases with MUC6 expression in our series is similar to a recent report that shows MUC6 expression in 40 % of breast carcinoma cases; however, an association between MUC6 expression and the clinicopathological variables was not identified." (PMID 27846863, 2016). "Interestingly, in vitro data generated in a study investigating pancreatic, colorectal, and breast cancer cell lines suggest that MUC6 may inhibit invasion of tumor cells through the basement membrane." (PMID 27298226, 2016). "For diagnostics purposes, antibodies associated with breast carcinoma include estrogen receptor (ER), progesterone receptor (PR), gross cystic fluid protein (GCDFP), HER-2/neu, cytokeratins (CK5/6, CK7, CK20), and the mucin glycoprotein antibodies, namely, MUC2, MUC3, MUC5AC, MUC6, and DAS-1." (PMID 24066246, 2013). "In breast cancer, most tumors express MUC1 and MUC3, and the expression of MUC2, MUC4, MUC5AC, and MUC6 is variable or limited." (PMID 27846863, 2016). "We have described clinicopathological characteristics of patients with breast cancer containing SRCs in relation to the expression levels of MUC1, MUC2, MUC4, MUC5AC, and MUC6." (PMID 27846863, 2016). "It has been shown using the two breast cancer cell lines MCF7 and T47D that MUC6 tandem repeats are good candidates for the high density of the common human cancer-associated Tn antigen found in these cell lines." (PMID 23056409, 2012).
gastritis (8 papers, 2021 to 2025). Inflammation of the stomach. "Among genes encoding mucins, Muc6 expression was significantly diminished under conditions mimicking acute gastritis." (PMID 41423315, 2025). "For example, the SNP rs7481521 of the MUC6 gene showed a significant decrease in risk for homozygous carriers and a clear relationship between the number of alleles and chronic atrophic gastritis." (PMID 37581476, 2023). "The MUC6 SNP rs7481521 had a significant association with a decreased risk for homozygous carriers and a significant dose-response relation with the number of alleles in chronic atrophic gastritis patients." (PMID 36118520, 2022). "The localized expression of Muc6 underscores its specific role in maintaining gastric mucosal integrity, particularly during the onset of acute gastritis." (PMID 41423315, 2025). "Reduced αGlcNAc expression of MUC6, as determined by immunohistochemistry, occurs in chronic atrophic gastritis and pyloric gland adenoma, both of which are precursors to GAc." (PMID 37958425, 2023). "A connection was discovered between the expression of MUC6 SNPs and the onset of chronic atrophic gastritis and hepatocellular carcinoma." (PMID 37581476, 2023). "In the mouse model, oral administration of ICAC significantly alleviated acute gastritis by preserving mucosal integrity, preventing prostaglandin E2 depletion, and enhancing Ptgs1 and Muc6 expression in mice, while suppressing inflammatory mediator production in gastric tissues." (PMID 41423315, 2025). "Additionally, the expression of MUC6 is also up-regulated in spasmolytic polypeptide-expressing metaplastic regions (SPEM) in gastritis patients." (PMID 34795059, 2021). "α-Humulene may attenuate HCl/ethanol-induced gastritis by inhibiting histamine release and NF-κB activation and stimulating antioxidants and mucosal protective factors, particularly Muc5ac and Muc6." (PMID 34064830, 2021). "In particular, LCN2 expression levels were higher in MUC6+, MUC5AC+, proliferation cells, and in the chief cells in pre-GC and GC than gastritis." (PMID 40520011, 2025).
chronic atrophic gastritis (6 papers, 2006 to 2025). Atrophic gastritis that is persistent and long-standing. "In our study, both the IRS and ODS scores for MUC6 expression in the glandular epithelium were significantly higher in patients with gastric atrophy." (PMID 33322136, 2020). "The expression of MUC6 was significantly higher in patients with gastric atrophy." (PMID 33322136, 2020). "Among studies that included pediatric patients, the expression of MUC5AC, MUC6 and MUC2 were all increased in patients with intestinal metaplasia, but no data was available for gastric atrophy." (PMID 33322136, 2020).
colitis (6 papers, 2010 to 2025). Inflammation of the colon. "Bifidobacterium breve UCC2003 was shown to increase and mucus layer generation genes including Muc2, Muc6, Muc5c, and Muc4 and Gja1 and Gjb8 in the mucosa-associated with DSS colitis." (PMID 39849930, 2024). "Studies on DSS-induced colitis also report that KO supplementation increased the mRNA expression level of Muc6 (Mucin 6), TJ-related genes, claudin-1, occludin, and zonula occludens (ZO)-1, and reduced serum levels of LPS and diamine oxidase (DAO), indicating a decrease in intestinal permeability." (PMID 38672464, 2024). "Theoretically, this could diminish protection of the colonic stem cells by the Tff2/Muc6 complex and could lead to increased susceptibility of Tff1KO mice to DSS-induced colitis, similarly to what has been reported for Tff2KO mice." (PMID 37628863, 2023). "Moreover, TNF-α upregulated the expression of mucin secretion and increased the expression of MUC6, contributing to the defective mucus layer in colitis." (PMID 33807999, 2021).
mucinous adenocarcinoma (6 papers, 2010 to 2024). An invasive adenocarcinoma composed of malignant glandular cells which contain intracytoplasmic mucin. "In contrast, mucinous carcinomas originating from the upper gastrointestinal tract exhibit high MUC6 expression, with a positivity rate of 76% (31/41 cases)." (PMID 39040449, 2024). "MUC6 inversely correlated with tumor differentiation and mucinous adenocarcinoma subtype." (PMID 27298226, 2016). "Mucinous adenocarcinoma (a more aggressive LC subtype) showed higher expression of secretory mucins, including MUC2, MUC5AC, and MUC6." (PMID 36980526, 2023). "Mucinous carcinoma of breast predominantly expresses the secretary mucins, MUC2 and MUC6." (PMID 20550696, 2010). "In a study comparing 7 mucinous adenocarcinomas (previously known as mucinous bronchioloalveolar carcinoma (mBAC)) and 27 non-mucinous BAC, higher levels of MUC2, MUC5AC, and MUC6 expression were found in mucinous BAC." (PMID 36367122, 2023).
pyloric gland adenoma (6 papers, 2012 to 2026). A rare neoplastic polyp that arises from the stomach. "Pyloric gland adenoma (PGA) is a duodenal neoplasm expressing MUC6 and is often associated with high-grade dysplasia and adenocarcinoma." (PMID 38062108, 2023). "Pathological examination of the resected specimen revealed that a pyloric gland adenoma, which was positive for MUC6 and MUC5AC, had detached from its mucosal stalk, leading to significant hemorrhage." (PMID 42078163, 2026). "Duodenal neoplasms show intestinal or gastric gland differentiation, and among the latter, pyloric gland adenoma (PGA) is the major subtype and is highly positive for MUC6 and more variably for MUC5AC2–4." (PMID 38062108, 2023). "These tumours did not arise from pyloric gland adenomas, but displayed a similar immunophenotype with positive expression of MUC5AC and MUC6 and negativity for MUC2 and CDX2." (PMID 23206236, 2012). "The pyloric gland adenoma showed focal positive staining for MUC1, and negative staining for MUC2, as well as superficial staining for MUC5AC, and positive expression of MUC6 and VEGF." (PMID 23206236, 2012).
colon cancer (5 papers, 2016 to 2025). "When evaluating new biomarkers for colon cancer, MUC1, MUC2, MUC4, MUC5AC, and MUC6 are currently documented in the largest bodies of work regarding their role in the progression from normal colonic tissue to malignancy." (PMID 36900282, 2023). "Further prospective studies evaluating adjuvant chemotherapy in stages II and III colon cancer should include MUC2, MUC5AC, and MUC6 expression analysis for patient stratification." (PMID 27298226, 2016). "Studies on the immunohistochemistry of colon cancer also revealed that the low expression of MUC2 is associated with colon tumor and less favorable disease outcome, and lack of expression of MUC5AC and MUC6 were associated with worsened stages of CRC." (PMID 40699805, 2025).
dysplasia (5 papers, 2014 to 2023). A usually neoplastic transformation of the cell, associated with altered architectural tissue patterns. "Specifically, during normal esophageal squamous, BE metaplasia, dysplasia, and EAC progression there is a progressive increase in TFF2, TFF3, MUC2, MUC5AC, MUC6, CDX2 with the development of intestinal metaplasia." (PMID 36994101, 2023). "Contrary to this, it was also reported that increased expression of MUC6 lacks specificity in distinguishing SSA/P and SSA/P with dysplasia from HP." (PMID 27705923, 2017). "We performed immunostaining for β-catenin, MLH1, and mucins (e.g., MUC2, MUC5AC, MUC6, and CD10); targeted next-generation sequencing; and microsatellite instability (MSI) testing in 8 SSA/P lesions comprised of 4 SSA/Ps with high-grade dysplasia and 4 SSA/Ps with submucosal carcinoma." (PMID 30458818, 2018).
inflammatory bowel disease (5 papers, 2013 to 2024). A spectrum of small and large bowel inflammatory diseases of unknown etiology. "We identified MUC6+ metaplastic cells from inflamed intestines from patients with inflammatory bowel disease (IBD) and coeliac disease, uncovering the full transcriptome of pyloric gland metaplastic cells, which we termed inflammatory epithelial cells (INFLAREs)." (PMID 39567783, 2024). "The full sequences of these mucins will now allow such studies, which could be of importance for inflammatory bowel diseases for MUC2 and gastric ulcer diseases for MUC6 where deficient mucus protection is assumed to play an important role." (PMID 30504806, 2018). "Gel-forming mucins (particularly MUC5AC and MUC6) may play a role in epithelial wound healing after mucosal injury in inflammatory bowel disease, in addition to providing mucosal protection." (PMID 24829572, 2014). "The gel-forming mucins (particularly MUC5AC and MUC6) may have a role in epithelial wound healing after mucosal injury in inflammatory bowel disease, in addition to providing mucosal protection." (PMID 23691335, 2013). "Moreover, MUC6 may play a role in epithelial wound healing after mucosal injury in inflammatory bowel diseases in addition to mucosal protection." (PMID 33807999, 2021).
cholangiocarcinoma (4 papers, 2020 to 2023). A carcinoma that arises from the intrahepatic biliary tree (intrahepatic cholangiocarcinoma) or from the junction, or adjacent to the junction, of the right and left hepatic ducts (hilar cholangiocarcinoma). "Moreover, MUC6 mutations were found in Epstein–Barr virus (EBV)-associated lymphoepithelioma-like cholangiocarcinoma, and directly associated with thyroid cancer." (PMID 37504272, 2023). "For example, immunohistochemical MUC6 positivity ranges from 7% to 85% in esophageal adenocarcinoma, from 4% to 93% in cholangiocellular carcinoma, from 24% to 64% in pancreatic ductal adenocarcinoma, from 20% to 100% in cervical adenocarcinoma, and from 0% to 92% in lobular breast carcinoma." (PMID 37057870, 2023). "Importantly, abnormal expression of MUC6 was reported to be associated with many gastrointestinal cancers, such as HCC and cholangiocarcinoma." (PMID 32117713, 2020). "MUC1 showed high expression in cholangiocarcinomas and cholangiocellular differentiated areas of cHCC-CCC, whereas MUC2, MUC3, MUC5/6, MUC5AC, MUC6, and MUC7 showed limited usefulness for further differentiation." (PMID 36672443, 2023).
gastric tumor (4 papers, 2021 to 2025). "Specifically, Kaplan–Meier curves indicated that low mRNA expression of MUC5AC and MUC6 in gastric tumor tissue correlated with worse survival (P ≤ 0.027)." (PMID 37085819, 2023). "This was corroborated by significantly lower levels of MUC6 expression in advanced and poorly differentiated gastric tumour specimens, than normal and pre-malignant tissue in their study (p < 0.01)." (PMID 37958425, 2023). "Associated to mucins, too, is the family of trefoil factors, including the gastric tumor suppressors TFF1 and TTF2, which are co-localized with MUC5AC and MUC6, respectively; and TFF3, which is typically not secreted by gastric mucosa but, like MUC2, by goblet cells." (PMID 34227026, 2021).
hepatocellular carcinoma (4 papers, 2020 to 2023). A malignant tumor that arises from hepatocytes. "In our previous study, we found that genetic variations in MUC6 may correlate to hepatocellular carcinoma and indicate the progression in hepatocellular carcinoma patients." (PMID 37581476, 2023).
lymph node metastasis (4 papers, 2014 to 2023). "MUC6 expression was related to lymph node metastasis (high for positive lymph node metastasis, p = 0.021)." (PMID 24722639, 2014). "MUC2 and MUC6 have been related to lymph node metastasis in LUAD patients." (PMID 36059804, 2022). "However, MUC6 expression within CRC is lower (up to 39%) compared to other mucins such as MUC1, which is expressed in 84% of patients with lymph node metastases." (PMID 36900282, 2023). "In GAS patients, we did not observe significant differences in clinicopathological findings, such as patient age, FIGO stage, lymph node metastasis and ascites cytology, between cases positive or negative for MUC6, αGlcNAc and α4GnT markers." (PMID 31506488, 2019). "For mucins with equal expression in SBC lesions and normal tissue, MUC4 expression was not related to any prognostic factors, but MUC6 was related to lymph node metastasis." (PMID 24722639, 2014). "In SBCs, however, MUC6 expression had no impact on survival, although it was related to lymph node metastasis." (PMID 24722639, 2014).
pancreatic ductal carcinoma (4 papers, 2005 to 2023). "MUC6 is shown to be associated with pancreatic ductal carcinoma and small intestine cancer." (PMID 35439935, 2022).
prostate carcinoma (4 papers, 2004 to 2024). A carcinoma that arises from epithelial cells of the prostate gland. "MUC6 has been associated with prostate carcinoma in the UAE population, hence promoting tumorigenesis." (PMID 36979105, 2023). "Of note was PI3K family members: PIK3C2G, PIK3CA, PIK3CB, PIK3R4, Mucin family members: MUC1, MUC4 and MUC6 and other prostate cancer associated genes such as SMAD4, SOX9 and SPOP7,9,40,41." (PMID 32796921, 2020). "Highly expressed genes defining the IDCP cluster, such as MUC6, MYO16, NPY, and KLK12, reflected the aggressive nature of high-grade prostate cancer." (PMID 38732035, 2024). "The loss of hormone dependence in this prostate cancer xenograft model is therefore marked by irreversible histological alterations, mucinous or neuro-endocrine, associated with an expression of secretory MUC2, MUC5B and MUC6, independent of the histological differentiation subtype." (PMID 14760390, 2004).
Barrett's oesophagus (3 papers, 2014 to 2023). "Additionally, reduced expression of αGlcNAc relative to MUC6 in Barrett’s oesophagus may be indicative of progression to OAc." (PMID 37958425, 2023).
Crohn disease (3 papers, 2015 to 2024). A gastrointestinal disorder characterized by chronic inflammation involving all layers of the intestinal wall, noncaseating granulomas affecting the intestinal wall and regional lymph nodes, and transmural fibrosis. "A scRNA-seq study of paediatric treatment-naive patients with Crohn’s disease identified MUC6+TFF2+ and BPIFB1+AQP5+ populations, albeit annotated as goblet cells." (PMID 39567783, 2024). "Metaplastic changes of gastric type, with special reference to MUC6-positive “pyloric” glands, have long been reported in Crohn’s disease intestinal mucosa." (PMID 33963925, 2021). "We located INFLAREs (MUC6+AQP5+BPIFB1+) at the crypt base and surface foveolar cells (MUC5AC+) at the crypt top of metaplastic glands in Crohn’s disease mucosa." (PMID 39567783, 2024). "In Crohn ́s disease, MUC5AC expression is known to be induced in the intestine together with MUC5B and MUC6." (PMID 26162072, 2015).
cyst (3 papers, 2015 to 2025). A sac-like closed membranous structure that may be empty or contain fluid or amorphous material. "The O-linked glycomes of acidic glycoproteins from cyst fluids were found to be similar to oligosaccharide structures from a previously defined O-glycome of gastric mucins MUC5AC and MUC6, which were isolated from gastric tissues of healthy humans." (PMID 26075384, 2015). "DEST analysis for EV in these matched samples demonstrated low plasma and cyst fluid expression for the malignant biomarkers Das-1, MUC5AC, and MUC6." (PMID 37414831, 2023).
cystic fibrosis (3 papers, 2015 to 2020). Autosomal recessive disorder caused by pathogenic variants in the CFTR gene (cystic fibrosis transmembrane conductance regulator), which encodes a chloride and bicarbonate channel expressed in epithelial cells, and follow the diagnosis criteria. "Burkholderia, a gram-negative bacterial genus, is recognized as an important pathogen in the mucus-filled lungs of patients with cystic fibrosis; it was linked to gene MUC6, which encodes a secreted protein responsible for the production of mucin." (PMID 32571363, 2020). "MUC6 has been detected in developing pancreas and in small pancreatic ducts in patients with cystic fibrosis and concomitant chronic pancreatitis, while its role in the pathophysiology of pancreatitis remains unclear." (PMID 25803032, 2015).